CDX2 (caudal type homeobox 2)
Diseases named in the same sentence as CDX2 in open-access papers (continued):
Sharing a sentence is not in itself a finding about the gene and the disease.
tumor (continued). "In our case the tumor was positive for CEA, CK 7 and TTF-1 and negative for CK 20, ER, COX2, CK 14, CDX2, and MUC2." (PMID 24716057, 2014). "Immunohistochemically, the tumor cells were diffusely positive for pancytokeratin (AE1/AE3), focally positive for lipase and trypsin, and negative for cytokeratin 7, cytokeratin 20, CDX2, and endocrine markers such as chromogranin, synaptophysin, and CD56." (PMID 24550989, 2014). "Tumor cells were negative for both CK20 and CDX2, specific markers of adenocarcinoma of intestinal origin." (PMID 24550989, 2014). "Immunohistochemical analysis revealed that these tumor cells tested positive for CK7, CK20 (weakly), MUC5AC, MUC6, CDX2 (patchy), CEA, and CA19-9 and negative for MUC2, ER, and PgR." (PMID 25386374, 2014). "Immunohistochemical analysis (IHC) revealed that those tumor cells tested positive for CK7, CK20 (weakly), MUC5AC, CEA, and CA19-9 and negative for MUC2, MUC6, and CDX2." (PMID 25386374, 2014). "CK7 and CK20 were both negative in our case, but positive CDX2 and MUC2 confirmed the tumor’s urachal origin." (PMID 23914849, 2013). "In the third objective, we explored whether CDX2 pCTCs can be found in other cancers because currently one major limitation in IE CTCs detection is that only broad-spectrum antibodies are used and therefore detection is not specific to any kind of tumour or tissue system." (PMID 21364588, 2011). "In morphologically determined pancreatobiliary-type adenocarcinomas (n = 67), most tumours (58 of 65) had diffuse CK7 expression (in >40% of the tumour cells) or were largely negative for MUC2 (62 of 65) and CDX2 (57 of 65)." (PMID 19236510, 2009). "Immunohistochemistry showed strong membrane positivity for cytochrome 7 (CK7) (>90% tumor cells), cytochrome 20 (CK20)- focal membrane positivity in >20% tumor cells, cytochrome 19 (CK19)-focal positivity in 50-60% cells, and caudal type homeobox 2 (CDX2) was negative." (PMID 39669837, 2024). "Tumor cells were also positive for TTF1 and negative for CDX2, favoring lung origin." (PMID 39130860, 2024). "The tumor cells were immunohistochemically positive for cytokeratin 7 (CK7), gross cystic disease fluid protein 15, GATA-binding protein 3, human epidermal growth factor receptor 2, and androgen receptor and negative for CK20, CK5, p63, S100, and CDX2." (PMID 39310547, 2024). "Immunohistochemical studies showed the tumor cells were negative for CK7, CK20, and CDX2." (PMID 39604765, 2024). "Immunohistochemical results showed the tumor cells were negative for CK7, CK20, and CDX2." (PMID 39604765, 2024). "It should be mentioned that non-CRC with intestinal differentiation or of mucinous type were recognised to express high rates of CDX2 and/or CK20 opposed to SATB2 that frequently addressed negative expression in those tumours even if they show intestinal differentiation." (PMID 36819801, 2022). "Interestingly, the tumor-related markers pan-CK, CEA, and CDX-2 were widely expressed in non-SRCC G04 organoids and primary tissues." (PMID 35013129, 2022). "Finally, studies revealed that the immunohistochemical profile of the tumor did not allow to distinguish between PMP of primitive ovarian or digestive origin, both of them being positive for CK20 and CDX2 with variable staining for CK7." (PMID 34930348, 2021). "When CK7 and CDX2 expressions were combined, patients with CK7-positive and CDX2-negative tumours showed the worst outcome, while patients with CK7-negative and CDX2-positive tumours showed the best survival, with intermediate figures for the double-positive or double-negative tumours." (PMID 33963925, 2021). "The tumor cells were negative for CK20 and CDX2 and positive for CK7, TTF1, and PAX8 markers." (PMID 30087814, 2018).
tumor (continued). "Immunostaining for CK-CAM5.2, and CDX2 were positive and CK7 and CK20 were negative indicating enteric differentiation of the tumor cells, and primary tumor location might be gastrointestinal tract." (PMID 29801472, 2018). "Taken together, the noted signaling differences and lack of progression to adenocarcinoma in CDX2;APC;PID mice suggests that Group I Pak kinase activity is a key factor in tumorigenesis and the expression of PID peptide is sufficient to impede tumor progression in this CRC mouse model." (PMID 30150766, 2018). "Because the 395 CRCs were represented as very limited tumor regions in the tissue microarray format, we could not reliably assess relationships of PDX1, CDX2 and ANXA10 staining in these CRCs relative to serrated morphology features." (PMID 28072391, 2017). "Immunohistochemically, the tumor was strongly positive for keratin 7 (CK7) and pankeratin AE1/AE3, and alpha 1 antichymotrypsin; negative for synaptophysin and chromogranin A, CDx2, CK20, S100, carcinoembryonic antigen (CEA), MUC 2, MUC5AC, and somatostatin; and in part positive for CA19-9." (PMID 29145864, 2017). "Tumor cells were positive for CK7 EMA, CKAE1/AE3, CD15, CA-125, while immunoreaction for Calretinin, WT1, estrogen, and progesterone receptors, cytokeratin 20, CD10, alpha fetoprotein, CDX2, TTF1, and thyroglobulin were all negative." (PMID 27912770, 2016). "The tumor cells were immunoreactive for cytokeratin 7 (CK7), thyroid transcription factor-1 (TTF-1), and napsin A and were negative for CD20, CDX2, P63, chromogranin, synaptophysin, and CD56." (PMID 26425638, 2015). "High tumor grade, high T and N Stage, lymph node ratio (LNR), perineural and vascular invasion were significantly less frequent and expression of intestinal molecular markers CK20 and CDX2 was significantly higher with INT versus non-INT adenocarcinoma." (PMID 24053229, 2013). "Additionally, some other loci showing significant differences in DNA methylation levels between tumor and non-tumor lung tissue have been identified, including: CDKN2A EX2, CDX2, HOXA1, SFPR1, and TWIST1 gene." (PMID 23086271, 2013). "However, silencing cdx-2 gene with siRNA and subsequent activation with ephrin-A1 or transfection with pcDNA-EFNA1 failed to inhibit tumor growth in A549 cells." (PMID 22824143, 2012). "If CDX2 and SATB2 are both negative, or if CK7 is positive but CK20 and TRPS1 are negative, third-tier immunostains including p63, GATA3, uroplakin II/III, PSA, and NKX3.1 should be performed to further classify the tumor as urothelial or prostatic secondary EMPD." (PMID 41463263, 2025). "Furthermore, the tumor cells were positive for cytokeratin (CK) 19; partially positive for thyroid transcription factor-1 (TTF-1); and negative for Pax-8, Napsin A, CDX-2, SATB2, and terminal deoxynucleotidyl transferase (TdT)." (PMID 33847622, 2021). "In addition to the antigens described here, the original tumor was positive for CKC, CK7 and CK 5/6, negative for GATA3, CDX2, ERα, CK20,p63, AFP, CA19.9, TTF1 and PAX 8 and with patchy/focal staining for calretinin, CD10, RCC, BerEP4 and WT‐1 (data not shown)." (PMID 30109783, 2018). "The exclusion of genes like BCL2L10, OR10J6P, CDX2, and MT2P1 from the PPI network due to lack of interaction data may also warrant further investigation into their specific molecular functions or how their roles might be context-dependent within the tumor microenvironment." (PMID 39766765, 2024).
cancer (213 papers, 1999 to 2025). A tumor composed of atypical neoplastic, often pleomorphic cells that invade other tissues. "Keratins, a family of structural proteins increasingly recognized as diagnostic markers in cancer progression, were the primary driver proteins that stratified samples based on CDX2- stromal cells." (PMID 39252972, 2024). "Fok1 (rs10735810), Bsm1 (rs1544410), Apa1 (rs7975232), Taq1 (rs731236), and Cdx2 (rs11568820) genes are among the most extensively studied VDR SNPs associated with cancer." (PMID 39335182, 2024). "VDR polymorphism (Apa1, Cdx2, and Taq1) is associated with an increased risk of developing various cancer types, including CRC, BCC, SCC, HCC, head and neck cancers, kidney cancers, and thyroid cancer." (PMID 39335182, 2024). "In contrast, other DNA damage response and repair genes, including BRCA1, BRCA2, ATM, BRIP, POLQ, and CDK12, were significantly more often mutated in CDX2-suppressed cancers." (PMID 39452477, 2024). "In our study, there was an increase in the percentage of cases with loss of CDX2 expression as the cancer stage advanced, i.e., stages I (3.5%), II (5.0%), III (10.7%) and IV (12.1%), which was statistically significant (p = 0.015)." (PMID 39201360, 2024). "High intraepithelial CD3+ and CD8+ scores and high stromal CD3+ and CD8 + TIL scores were all individually significantly associated with a lower stage, CDX2 negativity, right-sided cancer, the dMMR phenotype, and PD-L1 positivity." (PMID 36110945, 2022). "PRDM1-deficient cancer cells displayed marginal expression of CDX2 in response to ribosomal dysfunction, indicating a positive regulation of CDX2 by PRDM1." (PMID 33972671, 2021). "Caudal-related homeobox transcription factor 2 (CDX2), an intestine-specific nuclear transcription factor, has been strongly implicated in the tumourigenesis of various human cancers." (PMID 30631044, 2019). "In human disease, it appears that loss of CDX2 is an early event in the progression of cancers via the serrated pathway." (PMID 30257705, 2018). "Fine-mapping of the CRC associated variants in SCG5-GREM1 locus showed that a functional SNP acted as an allele-specific GREM1 enhancer and influenced cancer risk through differential CDX2 and TCF7L2 binding." (PMID 28977865, 2017). "Third, we excluded the low-quality trials conducted by Jamieson 2013 and Wong 2011, and the results of CDX2 expressions that were associated with OS and cancer relapse remained stable." (PMID 29179508, 2017). "Results from a recent published meta-analysis indicated that individuals who carry variant AA homozygote Cdx2 had a nearly 16% increased risk of cancer." (PMID 25849303, 2015). "In the subgroup analysis by ethnicity, results indicated that the association between Cdx-2 polymorphism and cancer risk is different in Caucasians and African Americans, suggesting genetic diversity among ethnicities." (PMID 25849303, 2015). "One hundred and seventy-four patients had MMR-proficient cancers, of which 60 (34.5%) showed Cdx2 loss." (PMID 24130965, 2013). "We also show that the unfavorable impact of Cdx2 is maintained in patients with MMR-deficient cancers." (PMID 24130965, 2013). "Cdx2 loss among patients with MMR-proficient cancers was significantly and unfavorably related to survival (p = 0.0102)." (PMID 24130965, 2013). "There were 174 patients with MMR-proficient cancers, of which 60 (34.5%) indeed showed loss of Cdx2." (PMID 24130965, 2013). "The protein expression of Cdx2 in MMR-proficient versus deficient cancers has been reported at 84 versus 61% on average, again using tissue microarrays." (PMID 24130965, 2013). "Cdx2 encodes a transcription factor that promotes intestinal differentiation; ectopic expression of Cdx2 in the esophagus can help promote metaplasia and cancer." (PMID 21935353, 2011).
cancer (continued). "For the Cdx2 polymorphism, a predisposition to osteoporosis and cancer development has been found." (PMID 40710536, 2025). "Common mutations in DDR-associated genes, such as BRCA2 and ATM, in CDX2-suppressed cancers may offer additional therapeutic opportunities for treatment with PARP inhibitors or inhibitors of ATM that are in development." (PMID 39452477, 2024). "In addition, CDX2-suppressed cancers had a higher prevalence of mutations in several receptor tyrosine kinase genes, including EGFR, ERBB3, ERBB4, RET, and ROS1." (PMID 39452477, 2024). "In addition, several genes of the parallel PI3K/AKT pathway were more frequently mutated in CDX2-suppressed cancers, with the differences for PTEN, MTOR, and RICTOR reaching significance." (PMID 39452477, 2024). "CDX2 downregulation was associated with high-grade, advanced cancers with liver metastases." (PMID 37719843, 2023). "However, studies are needed to assess its prognostic value within individual cancer stages, while controlling for the impact of the most clinically relevant parameters known to be associated with CDX2 expression." (PMID 29900672, 2018). "Taken together with previous reports on BRAF and CIMP, we hypothesize that Cdx2 loss may play an early role in the progression of cancers arising through the serrated pathway." (PMID 24130965, 2013). "Reduced Cdx2 expression has additionally been associated with increased migration and invasion of cancer cells and may play a role in the epithelial mesenchymal transition (EMT) by disrupting WNT pathway signaling." (PMID 24130965, 2013). "MMR-deficient cancers show frequent losses of Cdx2, a homeodomain transcription factor." (PMID 24130965, 2013). "Indeed, all MMR-deficient cancers with the exception of one case showed only focal positivity for Cdx2 expression." (PMID 24130965, 2013). "This review will focus on the function of Cdx2 and, less so, its paralogues, Cdx1 and Cdx4, and how genetically engineered mutations of these genes have provided us with animal models that have spurred our understanding of the important links between metaplasia and cancer." (PMID 31739541, 2019). "Of these, key cancer-associated genes shown to be upregulated by the SySa fusion were downregulated by TAK-981 treatment, including CDX2, HOXA10, SUZ12, TYMS, AURKB, and HOXC10 and SMC2." (PMID 40804185, 2025). "Our enteroendocrine cells have lower CDX2 expression compared to other cancer states in both pCRC and mCRC as well as in healthy colon." (PMID 40393458, 2025). "The WNT/APC/β-catenin pathway is a prominent cancer-related signaling pathway deregulated in gastrointestinal cancers and a regulator of CDX2 expression." (PMID 40149431, 2025). "PF exhibited selective anti-cancer activity in CDX2-low CRC PDOs (as determined based on a threshold that was determined using StepMiner81 cutoff; see STAR Methods), reflected by low IC50 values." (PMID 41118768, 2025). "In contrast, mutations in three other genes of the KRAS pathway, BRAF, SOS1, and NF1, were significantly more common in CDX2-suppressed cancers." (PMID 39452477, 2024). "Rare cancer biomarkers such as Pax8, Pax2, napsinA, carbonic anhydrase IX, claudin-4, Cdx-2, and others have been identified and studied thoroughly to help provide a better diagnosis of rare cancer." (PMID 38256274, 2024).
cancer (continued). "Non-CDX2-suppressed cancers were more commonly located in the rectum (30.1% of the cases), while CDX2-suppressed cancers were rectal in 12% of cases (Fisher’s exact test p = 0.001)." (PMID 39452477, 2024). "The rest of the CDX2-suppressed cancers belonged to the CMS4 group, which was also observed in a sizeable minority (18.3%) of non-CDX2-suppressed tumors." (PMID 39452477, 2024). "Chromosomal instability (CIN) was the most prevalent characteristic in non-CDX2-suppressed cancers (88%) versus 37.8% of cases in the CDX2-suppressed group." (PMID 39452477, 2024). "Similar to TCGA, CDX2-suppressed cancers showed more commonly (68.8%) a low CIN, as measured by the FGA score and a high TMB above 10 mutations/Mb, than non-CDX2-suppressed cancers." (PMID 39452477, 2024). "Seventy-five AoV cancers were analyzed for cytokeratin 7 (CK7), CK20, and causal-type homeobox transcription factor 2 (CDX2) expression by IHC staining." (PMID 38167037, 2024). "AoV cancer cases with characteristics of the INT subtype (CK7-/CDX2 +) had a better prognosis than those with the PB subtype." (PMID 38167037, 2024). "CDX2-suppressed cancers were predominantly (66.7% of cases) of the CMS1 consensus molecular sub-type and less frequently belonged to CMS4, while no cases of CMS2 and CMS3 were included in the group." (PMID 39452477, 2024). "A non-significant trend for a worse PFS for stage III patients with CDX2-suppressed cancer was observed (Log Rank test p = 0.12)." (PMID 39452477, 2024). "Primary location in the right colon was observed in 81% of CDX2-suppressed cancers, while only 43.4% of non-CDX2-suppressed cancers were located in the right colon (Fisher’s exact test p = 0.001)." (PMID 39452477, 2024). "The expression of CDX2 in IHC sections is used in clinical pathology for the confirmation of the colonic origin of cancers in biopsies, usually in combination with cytokeratins CK20, which is usually co-expressed in the colon, and CK7, which is not expressed." (PMID 39452477, 2024). "After analyzing the data collected from 192 independent studies (98,209 cancer-free controls and 78,628 cases), it was shown that Fok1, Bsm1, Cdx2, Apa1, and Taq1 are good markers for CRC, lung, ovarian, skin, multiple myeloma, and brain tumors." (PMID 39335182, 2024). "In contrast and consistent with the high frequency of CIN cancers in the non-CDX2-suppressed group, this group had a higher prevalence of cases with high AS and FGA scores." (PMID 39452477, 2024). "Representative sections from our case show heterotopic CDX2 positive nuclear staining in areas ranging from intestinal metaplasia to carcinoma." (PMID 39036214, 2024). "CDX2 was expressed more frequently in intestinal‐type cancers than in gastric‐, usual‐ and iSMILE‐type cancers (p < 0.001)." (PMID 35861118, 2023). "Although cancer stage was a powerful prognostic factor, CDX2 status was also an independent prognostic factor." (PMID 37602699, 2023). "Altogether, these lines of evidence suggest a novel regulatory pathway of H19/YAP/CDX2 in GC which can serve as a potential target for cancer therapy." (PMID 37005676, 2023). "We also confirmed that thapsigargin, an inducer of UPR, indeed suppressed the expression of cancer stem markers and instead enhanced the expression of the differentiation marker CDX2." (PMID 37152770, 2023). "Our study found that epithelial CDX-2 positive cells and Ki-67 positive cancer cells were negatively correlated with ECV, while collagen fibers were significantly positively correlated with ECV." (PMID 37546428, 2023). "The intestinal phenotype of AoV carcinoma, characterized by tubular or cribriform glands similar to those in colon cancer, exhibits expression of CDX2, MUC2, and CK20." (PMID 37783755, 2023). "subclassified AoV carcinoma based on CDX2 and MUC1 expression, finding that the PB phenotype (MUC1 positive and CDX2 negative) correlated with a poorer prognosis." (PMID 37783755, 2023).